SMARCB1 (SWI/SNF related BAF chromatin remodeling complex subunit B1)
Diseases named in the same sentence as SMARCB1 in open-access papers (continued):
Sharing a sentence is not in itself a finding about the gene and the disease.
cancer (continued). "Based on our results and on the review of individuals with SMARCB1 mutations in the literature, we suggest that the development of ID/neurodevelopmental disorders or malignant tumors could depend on a transcriptional compensation by the second intact SMARCB1 allele." (PMID 31273213, 2019). "An unresolved question is whether these cancers depend upon loss of SMARCB1." (PMID 30860482, 2019). "Targeting DCAF5 can suppress SMARCB1-mutant cancer by stabilizing the SWI/SNF complex, underscoring the critical connection between CUL4B and the SWI/SNF complex." (PMID 40203790, 2025). "Results of histopathological analysis revealed a heterogenous malignant neoplasia with embryonal characteristics and immunohistochemical loss of nuclear SMARCB1/INI1 expression, while SMARCA4/BRG1 staining was retained." (PMID 41168858, 2025). "SMARCB1 encodes a core subunit of the BAF (BRG1/BRM-associated factor) chromatin remodeling complex, and inactivating mutations are known to drive diverse cancers." (PMID 40120586, 2025). "Other malignant tumours observed in patients with SMARCB1-related SWN include papillary renal cell carcinoma and leiomyosarcoma." (PMID 40794298, 2025). "These carcinomas show complex genetic alterations, with homozygous SMARCB1 deletions present in the majority of cases." (PMID 40366517, 2025). "The prognosis for SDSNC is generally worse compared to its SMARCB1-retained carcinomas, particularly in advanced T4a/T4b disease." (PMID 39925590, 2025). "Lymph node puncture pathology results revealed poorly differentiated carcinoma consistent with SMARCB1/INI-1 deletion." (PMID 40115023, 2025). "In the present study, we show that simultaneous inhibition of two genes (CREBBP + EP300) causes synthetic lethality in cancers with a LOF mutation in another gene (i.e., SMARCB1)." (PMID 38839769, 2024). "Loss of SMARCB1 is also a genetic hallmark in rhabdoid tumours (RTs) where biallelic inactivation of SMARCB1 is often the sole driver of this aggressive paediatric cancer." (PMID 39237495, 2024). "Up to 25% of human cancers carry mutations in at least one of nine SWI/SNF subunit genes including SMARCA1 and 2, SMARCB1, ARID1A/B, PBRM1, and ARID2." (PMID 38085333, 2024). "CFT-8634 is a BiDACTM degrader targeting BRD9 for the treatment of BRD9-dependent cancers, including synovial sarcoma and SMARCB1-deleted cancers." (PMID 38256933, 2024). "LOF of the components of the SWI/SNF complex, mainly ARID1A, SMARCA4, or SMARCB1, has been demonstrated to sensitize cancer cells to PRC2 inhibitors." (PMID 39500892, 2024). "Current estimates indicate that 1.4% of all cancers contain SMARCB1 alterations (1152 of 84,646 queried samples found in AACR Project GENIE Cohort v11.0)." (PMID 38217014, 2024). "A meta-analysis of 10,849 patients from 15 studies found that 5% of human cancers had alterations in SMARCB1." (PMID 38085333, 2024). "SWI/SNF-complex-deficient malignancies can be determined by immunohistochemical staining with INI1 antibody for SMARCB1-deficient and BRG1 antibody for SMARCA4-deficient carcinomas." (PMID 38491228, 2024). "Malignant tumors with rhabdoid features are rare, highly aggressive, and some of them are characterized by SMARCB1 (INI1) loss." (PMID 36732357, 2023). "SMARCB1 mutated cells were found to be dependent on EZH2, a component of PRC2, and EZH2 inhibitors were tested with SMARCB1 mutated cancer patients in clinical trials." (PMID 37438850, 2023). "Studies have shown that BRD9 is preferentially used by cancers harboring SMARCB1 abnormalities, such as malignant rhabdoid tumors and several specific types of sarcomas." (PMID 36733714, 2023). "Mutations overlapping with those in cancer localize to the SMARCA4 ATP binding pocket and nucleosomal DNA-binding residues, the SMARCB1-CTD, and the SMARCA4-BAF core module entry point." (PMID 37500730, 2023).
cancer (continued). "Altogether, our comprehensive study shows that derailed activity of super-enhancers as a consequence of SMARCB1 loss underpins MRT tumorigenesis and serves as a blueprint for unraveling the contribution of BAF complex mutations to tumorigenesis across cancers." (PMID 38040699, 2023). "PRCC also displays mutations in previously studied cancer-related pathways; these include NF2 (Hippo pathway), SMARCB1 and PBRM1 (SWI/SNF complex), and chromatin modifier pathways (SETD2, KDM6A, and BAP1)." (PMID 38162463, 2023). "SWI/SNF complex-deficient carcinomas, defined by loss of one of the SWI/SNF complex genes, include two major subtypes: SMARCB1- and SMARCA4-deficient sinonasal carcinoma." (PMID 36937407, 2023). "Current estimates indicate that 1.4% of all cancers contain SMARCB1 alterations (1152 out of 84,646 queried samples found on AACR Project GENIE Cohort v11.0)." (PMID 35892904, 2022). "FISH analysis for the SMARCB1 locus and target exome sequencing for 425 cancer relevant genes were performed." (PMID 35804041, 2022). "With the advent of widespread sequencing technologies in cancer diagnosis, the number of diseases and subsequent cases that involve SMARCB1 alterations has grown." (PMID 35892904, 2022). "BRD9 is frequently amplified in cancer and is a vulnerability in cancer cells with inactivation of SMARCB1 or tumors having an oncogenic SS18-SSX fusion." (PMID 35323214, 2022). "Mutated SMARCB1 is unable to bind to NSD1 but binds to PRC2, leading to an increase in H3K27me3 with poor prognosis in cancer patients." (PMID 36589746, 2022). "Recently, we found that a major oncogene in cancer, MYC, becomes deregulated in MRT through loss of SNF5, a finding that explains the activation of MYC target gene signatures observed in SMARCB1-deficient cancers." (PMID 35650187, 2022). "About 2/3 of undifferentiated/dedifferentiated carcinoma show the loss of one of three crucial proteins of the SWI/SNF complex, i.e., ARID1B, SMARCA4/BRG1, and SMARCB1/INI1." (PMID 36232987, 2022). "Among them, 16 were SNUCs, four SMARCB1-deficient sinonasal carcinomas, one SMARCA4-deficient carcinoma, five high-grade neuroendocrine carcinomas, one NC, one TCS, and two sinonasal N-ITAC." (PMID 36431263, 2022). "This technology was applied to target BRD9, and the developed PROTACs dBRD9 and VZ185 were much more effective in treating SMARCB1-mutant cancers than their parent inhibitor BI-7273." (PMID 33941852, 2021). "A recent study demonstrated that the most frequent alterations of SMARCB1 in human cancer are the deletions." (PMID 33809336, 2021). "Broad-spectrum inhibitors have been successfully utilised in other cancers, such as dual inhibition of PDGFRa and FGFR2 by pazopanib in SMARCB1-deficient rhabdoid tumours." (PMID 34764236, 2021). "It was shown previously that SMARCB1 plays a vital role in the maintenance of normal cell adhesion and morphology in cancer and transformed cells, such as 293, MCF7, and NCCIT cells." (PMID 33125876, 2020). "Our study has established a new molecular link between SMARCB1 and IL6 in the immune reaction and highlights SMARCB1 as a key molecule in the development of treatment for inflammation-related diseases, including cancers." (PMID 32492816, 2020). "Overall, we suggest that future studies of the role of SMARCB1 in immunity be conducted considering both the functions of an immunostimulant and an immune suppressor in normal and cancer cells." (PMID 32492816, 2020).
cancer (continued). "SMARCB1 was the first SWI/SNF subunit discovered to be mutant in cancer and has been a focus of interest because of the extremely rapid and penetrant cancers that result from its inactivation." (PMID 31015438, 2019). "For the first time, with this work, we suggest that BRAF mutant/MSS cancers include the rare entity of CRbCs, characterized by a strong activation of EMT and complete loss or reduced expression of SMARCB1 (INI-1)." (PMID 31455041, 2019). "The majority are carcinomas (WHO grade III) and show SMARCB1 mutations that are predicted to result in a truncated protein." (PMID 31273213, 2019). "This complex can influence susceptibility to TOP2 inhibitor therapy as units like SMARCB1 are involved in loading TOP2A onto DNA, and thus can determine how many DNA breaks a cancer cell will have when exposed to a TOP2 poison." (PMID 29988316, 2018). "Consistent with the dependence of H3K27ac upon Smarcb1 deletion in MEFs, re-expression of SMARCB1 in the cancer cell lines resulted in increased global levels of H3K27ac (H3K27ac)." (PMID 28262751, 2017). "We identified deletions overlapping two known cancer susceptibility genes, (BRCA1 and BLM), and a duplication overlapping SMARCB1, associated with risk." (PMID 28302160, 2017). "This suggests that SMARCB1 expression can be reduced by multiple mechanisms, potentially leading to sensitivity in other cancer types." (PMID 27391784, 2016). "By showing that SMARCB1 loss also regulates PDGFRα expression levels, our study provides further evidence that exploiting RTK dependencies in cancers driven by SWI/SNF deficiencies is an effective therapeutic strategy in vitro." (PMID 27783942, 2016). "The first link between chromatin remodeling and cancer emanated from the discovery that SNF5 (SMARCB1/BAF47), a subunit of the human SWI/SNF remodeling complex, is inactivated in rhabdoid tumours." (PMID 26188466, 2016). "For instance, some germline variants in several well-known loss of function cancer driver genes such as DNM2, SMAD4, NF1, PTCH1, PTEN, SMARCB1, TSC1, cause dominant negative Mendelian diseases." (PMID 27080396, 2016). "To identify cancer-specific alterations, we first investigated the differences in SMARCB1/INI1 expression in CRCs and paired normal mucosa." (PMID 24286138, 2013). "This article will also serve to discuss the mechanisms by which aberrations of the SMARCB1 gene occur and their implications in driving the various hallmarks of cancer and provide an overview of the novel therapeutic approaches in clinical trials for treatment of RTs." (PMID 40422882, 2025). "In this study, we show that simultaneous inhibition of a paralog pair (CBP and p300) causes synthetic lethality in SMARCA4/SMARCA2-deficient cancer cells and SS18–SSX fusion cancer cells; these results are similar to those obtained for SMARCB1-deficient cancer cells." (PMID 39625239, 2025). "This approach may provide deeper insights into the dynamics of EGFR signaling and the role of SMARCB1 in modulating this cancer pathway." (PMID 39971779, 2025). "Conditional knockout of SMARCB1 leads to cancer formation in adult mice." (PMID 40115023, 2025). "Although a definitive histological diagnosis was not made, we diagnosed a malignant tumor with SMARCB1/INI1-deficient." (PMID 39398818, 2024). "After depletion of DCAF5, SMARCB1-deficient SWI/SNF complexes reaccumulate, bind to target loci, and restore SWI/SNF-mediated gene expression to levels that are sufficient to reverse the cancer state, including in vivo." (PMID 39125735, 2024).
cancer (continued). "In addition to the isogenic SMARCB1-deficient model, these CBP/p300 dual inhibitors, especially CP-C27, selectively sensitized SMARCB1-deficient cell lines in the cancer cell line panel to a greater extent than A-485 and inobrodib." (PMID 38839769, 2024). "The carcinomas were then evaluated immunohistochemically for SMARCB1 and SMARCA4 proteins." (PMID 39590317, 2024). "Carcinomas with a SMARCB1 deficit generally have a poor prognosis." (PMID 39398818, 2024). "Recently, a subset of carcinomas originating in the sinonasal tract has been identified with distinct biological aggressiveness, characterized by the complete loss of SWI/SNF complex subunits, particularly SMARCB1 (INI1) and SMARCA4 (BRG1)/SAMRCA2." (PMID 39590317, 2024). "Several synthetic lethal relationships have been described in altered SWI/SNF-driven cancers whereby cell viability upon the loss of one subunit (e.g., SMARCA4, SMARCB1, ARID1A) uniquely relies on the presence of either other SWI/SNF paralog subunit or a downstream gene or cellular pathway." (PMID 36810086, 2023). "Not only mutations but expression changes have also been reported for SMARCB1 in cancer." (PMID 37093326, 2023). "When grouping cancer genes into canonical cancer pathways, mutations in the SWI–SNF complex (for example, SMARCA4, ARID1B and SMARCB1) and certain members of the NOTCH signalling pathway (for example, EP300 and NCOR1) were under significant subclonal, but not truncal, selection in LUAD." (PMID 37046096, 2023). "Current literature does not definitively say if SMARCB1 deficient carcinoma responds similar as SNUC to IC, and some of the best studies looking at IC and SNUC do not mention these subtypes." (PMID 37568614, 2023). "The SWI/SNF genes, ARID1A, ARID1B, ARID2, SMARCA4, SMARCB1, and PBRM1 were mutated in up to 21.8% of all the cancers, and SWI/SNF mutation carriers had significantly higher TMB values as well as higher TMB-H and MSI-H proportions than their SWI/SNF-non-mutant counterparts in several malignancies." (PMID 36371186, 2022). "Thus, the inhibition of EZH2 using tazemetostat or GSK126 causes synthetic lethality in ARID1A-, SMARCA4-, SMARCB1-, PBRM1-deficient cancers." (PMID 36371186, 2022). "The boundaries between these high-grade adenocarcinomas and other high grade sinonasal malignancies like teratocarcinosarcoma or SMARCB1 deficient carcinomas are not well defined." (PMID 35326613, 2022). "These include NUT carcinoma, SMARCB1-deficient carcinoma, and SMARCA4 deficient carcinoma." (PMID 35326613, 2022). "In contrast to the non-glandular SMARCB1-deficient carcinomas, this variant displays more extensive and frequent expression of CK7 (83%) than p40 (33%)." (PMID 35307773, 2022). "Our two cases showed the absence of CD8+ TILs, whereas the SMARCB1-deficient carcinoma did express PD-L1." (PMID 36140305, 2022). "Given the exquisite sensitivity of SMARCB1-deficient cells to BRD9 inhibition, we hypothesized that BRD9/BRG1 peaks would occupy activate promoters associated with the hallmarks of cancer." (PMID 34071089, 2021). "While analyzing multiple cancer disorders, we found highly variable expression among genes implicated in cancer: EEF1A1, GNAS, NPM1, PIM1, and RHOA are known oncogenes; H3F3A, PTPRC, SMARCB1, and B2M are possible oncogenes; and CASP8, JAK1, and PRKAR1A are known tumor suppressor genes." (PMID 34174938, 2021). "SMARCB1 is a SWI/SNF chromatin regulatory tumor suppressor, and mutations in it or similarly functioning members of this family are relatively common in many cancer types, including lung." (PMID 33889302, 2021). "However, it has been reported that inactivating mutations in SWI/SNF subunits (ARID1A, PBRM1, SMARCB1, and SMARCA4) also sensitize cancer cells to T cell-mediated destruction." (PMID 32649682, 2020). "We hypothesized that the subset of genes co-regulated by SWINGN and SMARCB1 might contribute to the observed role of the lncRNA in promoting the proliferation of cancer cells." (PMID 32071317, 2020).
cancer (continued). "We also found that SMARCB1 knockdown induces cell cycle arrest with P21 upregulation in non-cancer cell lines ARPE19 and IMR90, suggesting that P21 could be a universal target of SMARCB1 to regulate the cell cycle." (PMID 32492816, 2020). "Additional mutations were identified in PIK3CA (six patients) and in HIST1H2BB, HIST1H2BC, and SMARCB1 (one patient each), but none were found in other frequently mutated genes in cancer." (PMID 32235312, 2020). "Potentially, a clinical trial could be run to see if they will treat patients whose cancers lack SMARCB1." (PMID 30860482, 2019). "Moreover, EZH2 inhibition blocks the progression of SMARCB1 mutant cancers in vivo, which has motivated the establishment of ongoing clinical trials with EZH2 inhibitors in RTs." (PMID 31123059, 2019). "Most MRTs are characterized by the loss of SMARCB1; however, carcinomas with rhabdoid features do not always involve the loss of SMARCB1." (PMID 30649642, 2019). "Altogether, adult-onset RT did not strikingly differ from other adult onset SMARCB1-deficient cancers from our series, all categories having a rather poor outcome." (PMID 28427232, 2017). "In addition to SMARCB1, other SWI/SNF subunits are often mutated in cancer like ARID1A in ovarian carcinoma, SMARCA4 (also known as BRG1) in lung and pancreas cancer, and PBRM1 in renal cancer." (PMID 27222667, 2016). "The ability of LIN28 and SMARCB1 to simultaneously regulate large sections of the genome and suppress senescence could spark the development of a malignant tumor such as AT/RT." (PMID 25638158, 2015). "Therefore, it was surmised by Bernard Weissman and others that the other SWI/SNF subunits must be involved in cancer akin to the SMARCB1 gene." (PMID 25774356, 2014). "Therefore, the cancer is not caused by the loss of SMARCB1 function per se, but rather by DCAF5-mediated degradation of the SWI/SNF complex." (PMID 40115023, 2025). "Our findings suggest that IHC may not be adequate for diagnosing a SMARCB1-deficient cancer, as point mutations can lead to non-functional proteins without complete loss of expression." (PMID 40196006, 2025). "Therefore, this study examined the potential for expansion and adaptation of simultaneous CBP/p300 inhibitors for use against cancers with SS18–SSX fusion and the majority of SMARCA4/SMARCA2-deficient in addition to SMARCB1 deficient, which was reported previously." (PMID 39625239, 2025). "The role of DCAF5 was confirmed by CRISPR-based competitive fitness assays and short hairpin RNA (shRNA)-mediated knockdown, showing that DCAF5 is required for the proliferation of SMARCB1-mutant RT lines, but not for cancer cells harbouring other SWI/SNF mutations." (PMID 39237495, 2024). "In addition, depletion of KREMEN2 reduced the viability of SMARCB1-deficient cell lines, but not that of SMARCB1-proficient cell lines, in the cancer cell line panel." (PMID 38839769, 2024). "Consequently, cancer results not from the loss of SMARCB1 function, but rather from DCAF5-mediated degradation of SWI/SNF complexes." (PMID 39125735, 2024). "Thus, simultaneous dual suppression of CREBBP and EP300, but not single suppression, causes synthetic lethality in SMARCB1-deficient cancers." (PMID 38839769, 2024). "Furthermore, mutations in SMARCB1 and SMARCA4 lead to widespread changes in the H3K27Me3 distribution, changing gene expression patterns, and suggesting that PRC2 can be targeted in these cancers." (PMID 37093326, 2023). "However, in those cancers where SMARCB1 is mutated the blockage of the bromodomain is not sufficient, requiring a complete degradation of BRD9, hinting to a need for structural disruption of ncBAF." (PMID 36810086, 2023). "Thus, while loss of SMARCB1 generally leads to widespread transcriptional repression, there appears to be a critical subset of genes driven by residual BAF complex activity that is required for cancer progression." (PMID 35892904, 2022).